AFM (afamin)
Diseases named in the same sentence as AFM in open-access papers (continued):
Sharing a sentence is not in itself a finding about the gene and the disease.
glaucoma (1 paper, 2011). Increased pressure in the eyeball due to obstruction of the outflow of aqueous humor. "Afamin (fold change, 3.3; p=0.0003) and gelsolin (fold change, 4.7; p=0.00005) were the 2 extracellular chaperones found to be differentially expressed in the AH of patients with glaucoma shunt device compared to normals." (PMID 21850163, 2011).
hyperandrogenism (1 paper, 2014). Excessive secretion of androgens from the adrenal glands or gonads. "Possibly, in a cohort with a higher degree of disease severity, e.g. more pronounced hyperandrogenism and more elevated HOMA-IR, a correlation between afamin and PCOS-specific features may occur." (PMID 24928911, 2014).
idiopathic nephrotic syndrome (1 paper, 2023). Nephrotic syndrome for which no cause has been identified. "Moreover, a study conducted on patients with idiopathic nephrotic syndrome in the pediatric population found that urinary afamin was significantly high." (PMID 36769494, 2023).
metastatic disease (1 paper, 2012). "Another promising candidate identified in our study was Afamin, which was found to be up-regulated in the non-progressing group compared with BPH group, but was down-regulated in the progressing and metastatic disease." (PMID 22355332, 2012).
myocardial infarction (1 paper, 2021). Gross necrosis of the myocardium, as a result of interruption of the blood supply to the area, as in coronary thrombosis. "Despite intensive research, the body of knowledge concerning kallistatin and afamin’s physiological and pathological properties in obese and myocardial infarction patients is still limited." (PMID 34945088, 2021). "In summary, the results of our study indicate that in the group of patients after myocardial infarction, significantly higher levels of kallistatin were observed, with simultaneously significantly lower levels of afamin." (PMID 34945088, 2021). "In conclusion, in this study, higher concentrations of kallistatin and lower levels of afamin were observed in the group of patients after myocardial infarction, after PCI, during cardiac rehabilitation." (PMID 34945088, 2021).
oligoasthenoteratozoospermia (1 paper, 2025). A form of male infertility that is characterized by a combination of low number or oligozoospermia, poor motility or asthenozoospermia, and abnormal shape or teratozoospermia of sperms. "Intriguingly, although human Afamin lacks intact LINE-1 sequences, it has been reported that Afamin protein levels in semen and serum are higher in patients with oligoasthenoteratozoospermia than in normal males." (PMID 40001600, 2025).
pneumonia (1 paper, 2013). An acute, acute and chronic, or chronic inflammation focally or diffusely affecting the lung parenchyma, caused by an infection in one or both of the lungs (by bacteria, viruses, fungi, or mycoplasma.). "Patients with pneumonia or sepsis exhibited markedly decreased afamin plasma concentrations." (PMID 23981841, 2013).
renal dysfunction (1 paper, 2023). "In the current study, multilinear regression shows the significant results of creatinine with afamin as compared to other parameters, depicting that afamin plays a pivotal role in renal dysfunction." (PMID 37835901, 2023). "Hence, serum afamin and investigations on other parameters such as serum phosphorous, Vitamin D, and serum calcium may act as diagnostic parameters to diagnose and check the progression of renal dysfunction in CKD patients and may act as a therapeutic target." (PMID 37835901, 2023). "So, the present study also supports the finding of the previous studies suggesting adropin and afamin may act as an add-on to the older laboratory biomarkers for assessing renal dysfunction and cardiovascular health in CKD patients." (PMID 37835901, 2023). "Adropin and afamin may have a significant independent potential role as novel biomarkers to predict the futuristic development of renal dysfunction and cardiovascular complications, which may further have the potential to act as a therapeutic target in future." (PMID 37835901, 2023).
synovitis (1 paper, 2025). Inflammation of a synovial membrane. "This study identified a lower SF concentration of afamin in high‐grade synovitis compared with low‐grade." (PMID 39972657, 2025). "For Thoroughbreds, gelsolin concentrations were lower for higher OA grades, and afamin was lower at a higher synovitis grade." (PMID 39972657, 2025). "However, the abundance of afamin was identified as differentially abundant between low and high‐grade synovitis, lower for higher‐grade synovitis severity." (PMID 39972657, 2025).
thyroid cancer (1 paper, 2023). "Serum afamin values have also been investigated in various types of carcinomas, including stomach, colorectal, cervix, liver, biliary tract, breast, and thyroid cancer." (PMID 36769494, 2023).
tumor (12 papers, 2013 to 2024). "Among the seven potential footrot-associated proteins, haptoglobin precursor, afamin precursor, apolipoprotein-D have been reported as tumor biomarkers." (PMID 23418487, 2013). "Regarding patients with CCA, a high level of afamin in plasma was correlated with poor outcomes after tumor resection." (PMID 32845921, 2020). "Furthermore, the level of afamin played a similar role, even more significant than the tumor stage, on the tumor recurrence and overall survival in CCA." (PMID 32845921, 2020). "Additionally, a set of genes, including AFM, DYNLRB2, FDX1, and SHBG, were significantly downregulated in HCC-R tumor tissues with fold changes ≥4 involved in various small molecule biochemistry and molecular transport mechanisms." (PMID 24377043, 2013). "Additionally, the tumor markers, which were found in the circulating system, could be CA19-9, α1β-glycoprotein, afamin, MMP-7, HYP, collagen I and γ-Glutamyltransferase, etc.." (PMID 34680259, 2021). "In contrast to previous studies, we did not observe an increase in afamin, clusterin, VDBP, or A1AT in the serum of tumor-bearing gp130Y757F mice versus wild-type in either early- or late-stage diseases." (PMID 38542101, 2024).
cancer (7 papers, 2012 to 2025). A tumor composed of atypical neoplastic, often pleomorphic cells that invade other tissues. "We chose these peptides because these genes, such as Annexin 2, Calprotectin A8, Calprotectin A9, Keratin 19, Keratin 8, Angiopoietin-1, Tissue inhibitor of metalloproteinase (TIMP), and Afamin, are associated with cancer progression." (PMID 36672532, 2022). "There are studies showing that afamin contains significant changes that can be used as a biomarker in both diagnosis and prognosis in certain types of cancer." (PMID 36769494, 2023).
metabolic disease (7 papers, 2019 to 2023). A congenital disorder (due to inherited enzyme abnormality) or acquired (due to failure of a metabolically important organ) disorder resulting from an abnormal metabolic process. "Taken together, afamin represents an excellent candidate biomarker for increased risk of metabolic disease." (PMID 34603196, 2021). "Afamin, ApoA4 and ApoA2 have previously been reported to be linked to the development of metabolic disease including one or more of T2D, DKD, or NASH as detailed below." (PMID 32830851, 2020). "Afamin is a member of the hepatokine that are strongly associated with various metabolic diseases." (PMID 35800214, 2022). "Here we provide evidence that complements previous reports and clearly indicates that afamin could serve as a marker of increased hepatic lipid content, which is tightly linked to metabolic disease development." (PMID 34603196, 2021). "Here we investigated regulation of afamin in a course of the metabolic disease development and in response to 3-month exercise intervention." (PMID 34603196, 2021). "Adropin, afamin, and neudesin may play a major role in the regulation of glucose metabolism and have a significant potential as novel biomarkers to predict future metabolic disorders." (PMID 31781629, 2019).
infection (3 papers, 2019 to 2025). The state of being infected such as from the introduction of a foreign agent such as serum, vaccine, antigenic substance or organism. "Upregulation of the Gc (afamin ortholog) in co-infected fish likely reflects enhanced antioxidant defense to counteract oxidative stress and metabolic demands during dual infection." (PMID 40943072, 2025). "Similarly, levels of Transferrin, Afamin, Fetuin A (Alpha-2-HS Glycoprotein), Fetuin B and Transthyretin were reduced in both infection types, and no statistical difference was found between their levels." (PMID 30774579, 2019).
neurodegenerative disease (1 paper, 2014). A disorder of the central nervous system characterized by gradual and progressive loss of neural tissue and neurologic function. "Thus alterations in afamin are not specific to neurodegenerative disease and quantitative changes are observed in other disorders as well." (PMID 24433274, 2014).
AFM also shares sentences with these, for which no sentence is quoted: preeclampsia (3 papers); chronic kidney disease (2); gastric cancer (2); Abdominal obesity (1); aortic aneurysm (1); asthma (1); atherosclerosis (1); autoimmune disease (1); cardiovascular disease (1); central nervous system disease (1); cholestasis (1); Cirrhosis (1); congenital disorder of glycosylation (1); coronary atherosclerosis (1); Down syndrome (1); endometrial cancer (1); epilepsy (1); focal segmental glomerulosclerosis (1); Hydrocephalus (1); Hyperglycemia (1); meningioma (1); Opportunistic infection (1); osteoporosis (1); pancreatic cancer (1); papillary thyroid carcinoma (1); Sepsis (1).